EIF4H (eukaryotic translation initiation factor 4H)
Description:
Stimulates the RNA helicase activity of EIF4A in the translation initiation complex. Binds weakly mRNA.
Synonyms: eIF-4H; KIAA0038; WBSCR1; WSCR1
Tractability: Small molecule: a high-quality ligand is known; it belongs to a druggable protein family. PROTAC: ubiquitination databases record sites on it; its protein half-life has been measured; a small molecule that binds it is known.
Target class: Other nuclear protein
Gene: Protein-coding gene on chromosome 7 (74,174,231 to 74,197,122, forward strand). Ensembl gene ENSG00000106682.
Subcellular location: Cytoplasm, perinuclear region
Subcellular location (Human Protein Atlas): Cytosol; Nuclear bodies; Nucleoplasm
Pathways (Reactome):
Metabolism of proteins: Activation of the mRNA upon binding of the cap-binding complex and eIFs, and subsequent binding to 43S; GTP hydrolysis and joining of the 60S ribosomal subunit; L13a-mediated translational silencing of Ceruloplasmin expression; Ribosomal scanning and start codon recognition; Translation initiation complex formation
Gene Ontology:
Molecular function: cadherin binding; protein binding; RNA binding; translation factor activity, RNA binding; translation initiation factor activity; nucleic acid binding
Biological process: regulation of translational initiation; translation; translational initiation
Cellular component: membrane; cytosol; eukaryotic translation initiation factor 4F complex; perinuclear region of cytoplasm
Genetic constraint (gnomAD): Loss-of-function variants: 8 observed, 28.45 expected, observed/expected ratio (o/e) 0.28, 90% interval 0.16 to 0.51. The upper end of that interval is the gene's LOEUF score, 0.51, which puts it in group 2 of 6, group 1 being the genes least tolerant of losing a copy. Missense variants: 188 observed, 325.6 expected, observed/expected ratio (o/e) 0.58, 90% interval 0.51 to 0.65. Synonymous variants: 106 observed, 115.27 expected, observed/expected ratio (o/e) 0.92, 90% interval 0.79 to 1.08.
Homologues: Orthologues: chimpanzee EIF4H (100% identical), macaque EIF4H (99% identical), rat Eif4h (98% identical), guinea pig EIF4H (96% identical), pig EIF4H (94% identical), dog EIF4H (93% identical), mouse Eif4h (91% identical), rabbit EIF4H (83% identical), tropical clawed frog eif4h (78% identical), zebrafish eif4h (78% identical), Drosophila melanogaster eIF4H1 (48% identical), Drosophila melanogaster eIF4H2 (41% identical), and 1 more. Paralogues in human: EIF4B (42% identical).